IL6 (interleukin 6)
Diseases named in the same sentence as IL6 in open-access papers (continued):
Sharing a sentence is not in itself a finding about the gene and the disease.
depression (continued). "Salidroside also significantly attenuated the levels of IL-6 and TNF-α in mice with depression-like behavior." (PMID 30705774, 2019). "Secretion of more proinflammatory cytokines [such as interleukin 6 (IL-6) and tumor necrosis factor alpha (TNF-α)] are reported in both patients with depression and animal models of depression." (PMID 31798446, 2019). "In our study, the levels of IL-1β, IL-6, and TNF-α were substantially increased in the hippocampus of the depression mice model induced by CUMS." (PMID 31068207, 2019). "Serum levels of interleukin-6 (IL-6), interleukin-33, C-reactive protein (CRP), tumor necrosis factor-α, and macrophage inflammatory protein-1β were found elevated in people with depression." (PMID 30899619, 2019). "Increases in biomarker levels were correlated with reduction in depression severity for TNF-α, IL-6 IL-10 and CRP." (PMID 31375659, 2019). "MDD: Major depressive disorder; SEM: Standard error of the mean; IL-6: Interleukin-6; CRP: C-reactive protein; Ham-D: Hamilton Depression Rating Scale; N: Number." (PMID 30899619, 2019). "Higher levels of interleukin (IL)-1β, IL-6, tumor necrosis factor (TNF)-α, and C-Reactive Protein (CRP) were reported in patients with depression by many investigators." (PMID 31252530, 2019). "A meta-analysis found that IL-1β, IL-6, TNF and C-reactive protein (CRP) in peripheral blood are the most reliable biomarkers of inflammation in patients with depression." (PMID 31849598, 2019). "A meta-analysis comprising 58 studies indicated that interleukin (IL)-6 and the acute phase reactant C-reactive protein (CRP) were elevated in major depressive disorder, and to a lesser extent, tumor necrosis factor (TNF)-α." (PMID 30967802, 2019). "Pro-inflammatory cytokines, such as interleukin (IL)-6 and tumor necrosis factor-α (TNF-α), are thought to play a fundamental role in the pathogenesis of depression within a subset of individuals." (PMID 30967802, 2019). "Further, a recent study has revealed that proinflammatory cytokines, such as IL-6, lead to depletion of the TRP pathways and therby induce depression-like behavior and decrease glutamatergic activity." (PMID 31251788, 2019). "Several behavioral tests (SPT, BW, FST and TST) and biochemical parameters (IL-6, TNF-α and SOD) were used to evaluate the antidepressive effects of PF on an LPS-induced depression model for the first time." (PMID 31052597, 2019). "For example, inflammatory proteins, such as C-reactive protein (CRP), and cytokines, such as interleukin (IL)-6 and tumor necrosis factor (TNF)-α, have been elevated in people with depression." (PMID 30987242, 2019). "A number of studies have indicated that various cytokines, such as IL-1β, IL-2, IL-6, TNF-α, and IFN-γ in serum or plasma of patients with depression were significantly increased." (PMID 31231295, 2019). "In a model of major depressive disorder, TNF-α expression is increased, and an antidepressant treatment decreases the expression of ADAM17 and its targets CXCL2 and IL-6." (PMID 30586315, 2019). "Excessive secretion of proinflammatory cytokines such as IL-1β, IL-6, and TNF-α triggers depression-like behavior; indeed, increased levels of such cytokines are found in the periphery and brains of patients with major depressive disorders." (PMID 31241715, 2019). "To probe the potential mechanism of the occurrence of depression, we also detect the expression of ABL1, NF-κB1, STAT3, IL-6, IL-1β, and COX2 in the hippocampus of depressive mice." (PMID 31396300, 2019). "The concentration of cytokines (IL-6, TNF-α, IL-17A, IL-10) was measured in the serum of healthy subjects and BD patients in remission or depression." (PMID 30971748, 2019). "Inflammatory markers such as IL-6 and C-reactive protein (CRP) are consistently found to be elevated in depression, although the size of the effect is relatively small." (PMID 31817800, 2019).
depression (continued). "Researchers have primarily been interested in studies on IL-6 and on the emotion-related traits of Extraversion and Neuroticism from the Five-Factor Model, as these traits may be one explanation for the frequently observed elevation of IL-6 levels in depression." (PMID 31798472, 2019). "A few postmortem brain studies suggest that expression of innate immune responders (IL-1β, IL-6, TNF-α) and TLRs are altered in postmortem brain of suicide victims, which includes suicide subjects with major depression." (PMID 30214045, 2019). "Several behavior tests (sucrose preference test (SPT), forced swimming test (FST) and tail suspension test (TST)) and biochemical parameters (IL-6, TNF-α and SOD levels) were used to evaluate the antidepressive effect of PF on LPS-induced depression model." (PMID 31052597, 2019). "The serum levels of proinflammatory cytokines such as interleukin 6 (IL-6), tumor necrosis factor α (TNF-α), and IL-1β are elevated in major depressive disorders." (PMID 30705774, 2019). "Some authors have reported a correlation between higher levels of IL-6 and TNF-α and depression scores (CES-D) in subjects displaying major depression, but not with high scores for stress perception in Afro-American and Caucasian pregnant women." (PMID 30943938, 2019). "The results showed that chronic unpredictable mild stress (CUMS) induces depression-like behavior in rats, accompanied by increased plasma concentrations of CRP and IL-6." (PMID 30429764, 2018). "Higher levels of IL-1β, IL-6, and TNF-α in the brain were believed to induce depression due to DAMPs under stress." (PMID 29765402, 2018). "It is also noteworthy that peripheral levels of IL-6 and CRP differentiate MS patients with depression from those free of depression." (PMID 29294244, 2018). "The activation of Janus kinase (JAK)-STAT signaling by IL-6 in circulating immune cells along with an increased circulating plasma indoleamine 2,3-dioxygenase (IDO) activity have been correlated to depression in patients." (PMID 29941796, 2018). "The pairwise comparisons of IL-6, TNF-α and CRP in patients with different depression degrees in observation group showed statistically significant differences (P<0.05)." (PMID 30181997, 2018). "IL-6 and TNF-α alter the metabolism of norepinephrine, serotonin, and dopamine and lead to symptoms of depression." (PMID 29619128, 2018). "Conditions such as depression, anxiety, and chronic stress can lead to an imbalance of the HPA axis and an increase of proinflammatory cytokines such as IL-6." (PMID 29854027, 2018). "The results of a meta-analysis of 24 studies measuring cytokines in depressed patients, found that individuals with Major Depression had significantly higher concentrations of Tumoral Necrosis Factor alpha (TNF-α) and Interleukin 6 (IL-6) compared to controls." (PMID 30108549, 2018). "Although many markers for depression had been identified previously, such as CRP, tumor necrosis factor-α (TNF-α), IL-6, the brain-derived neurotrophic factor (BDNF), and so on, the predictability of a single marker was poor." (PMID 30095631, 2018). "Meta-analyses have gathered large evidence, particularly with C-reactive protein (CRP), interleukin-6 (IL-6), tumour necrosis factor-α (TNF- α) and IL-1 receptor antagonist (IL-1ra) being elevated among patients with depression." (PMID 30126458, 2018). "Microglia release pro-inflammation mediators, such as IL-6, IL-1β, TNF-a, and nitric oxide that are considered links between chronic pain and depression." (PMID 30356873, 2018). "Proinflammatory cytokines like IL-1β, IL-6, TNF-α and IFN-γ are markers involved in the pathophysiology of depression." (PMID 29569964, 2018). "The proinflammatory cytokines IL-1, IL-6, and TNF-α are thought to play a primal role in the neurotransmitter and neuroendocrine changes that occur in depression given their central role in sickness behavior." (PMID 30093853, 2018).
depression (continued). "In the subset of depressed patients who exhibit elevated inflammatory cytokines, such as IL-6, IL-17, and TNF-α, targeted use of monoclonal antibodies against these cytokines can result in reduced anhedonia and overall depression severity." (PMID 29329256, 2018). "There is evidence to suggest that pro-inflammatory cytokines, including IL-1β, IL-6 and TNF-α, contribute to the onset and progression of depressive disorders." (PMID 29364170, 2018). "Convergent evidence of higher peripheral IL-1β, IL-6, TNF-α and CRP levels would support the psychoneuroimmunology theory as contributory to depressive syndromes and Alzheimer’s disease in elderly." (PMID 30104698, 2018). "In subjects exposed to higher levels of childhood life events, the transition to depression was accompanied by increases in CRP and IL-6." (PMID 28463238, 2017). "Many studies have shown that increased plasma concentrations of interleukin (IL)-1, IL-6, and tumor necrosis factor (TNF)-α were found in major depression patients with a history of poorer response to antidepressants than in treatment-responsive patients." (PMID 28832762, 2017). "Patients with major depression also often show increased inflammatory markers, including C-reactive protein (CRP), interleukin-6 (IL-6), and tumor necrosis factor (TNF)-α, relative to controls." (PMID 28670290, 2017). "The increasement of the pro-inflammatory cytokines such as CRP and IL-6 were found in patients with WMH, depression, stroke and PSD." (PMID 29051732, 2017). "The authors concluded that there is a positive correlation between depression and the increase of the three inflammatory cytokines: CRP, IL-1 and IL-6." (PMID 26649857, 2017). "A recent meta-analysis showed raised inflammatory markers such as IL-6 or C-reactive protein (CRP) are significantly associated with the subsequent development of depressive symptoms, which supports the hypothesis that there is an association between the inflammation and depression." (PMID 30886949, 2017). "In our study, we confirmed that increased IL-6 levels are indeed observed both in COPD and in depression and also when these diseases are comorbid." (PMID 26403459, 2016). "In addition, comparing patients with and without depression would build on the findings from a recent study showing significant associations between IL-6 concentrations and pain in patients with depressive symptoms, but not in patients without depressive symptoms." (PMID 27469518, 2016). "Interleukin-2 (IL-2) and interleukin 6 (IL-6) are two commonly used markers of inflammation, and increased expression of both IL-2 and IL-6 has been shown in cardiovascular disease, COPD, loneliness and depression." (PMID 29082106, 2016). "Considering these findings and also that rs1800795 is probably exerting its effect on IL-6 expression rate through a functional haplotype rather than alone, it seems unlikely to find either allele of the rs1800795 polymorphism to be exclusively associated with a depression phenotype." (PMID 26821321, 2016). "Interleukin (IL)-6 is a multifactorial cytokine known to be increased in patients with chronic hepatitis C (CHC) and to be predictive of depression incidence." (PMID 28083615, 2016). "Meta-analysis studies have reported higher levels of inflammatory cytokines (such as interleukin-6, (IL-6)) and acute phase proteins (such as C-reactive protein (CRP)) in the peripheral blood and cerebrospinal fluid of patients with major depression." (PMID 25877654, 2016). "It is thus unlikely that short-lived increases in cytokines playing a role in sickness behavior (such as IL-1β, IL-6, and TNF-α) will induce depression." (PMID 27504457, 2016). "The authors assessed IL-6 and CRP at baseline and depressive symptoms using the Center for Epidemiological Studies—Depression (CES-D) scale." (PMID 27918465, 2016).
depression (continued). "We confirmed that the M1 markers (IL-1β, IL-6, TNFα, iNOS, and CCL2) were induced and that the M2 molecules (Ym1, Arg1, IL-4, IL-10, and TGFβ) were impaired in depression." (PMID 27716270, 2016). "Pro-inflammatory cytokines such as IL-1β, IL-6, TNF-α, NF-κB, and iNOS have been demonstrated to induce abnormal behaviors, such as decreased locomotor activity, exploration, and depression, which was confirmed in our experiment." (PMID 27120616, 2016). "Secondary outcomes include serum biomarkers of SCI osteoporosis (sclerostin, P1NP and β-CTX), markers of immune function (IL-6, IL-10, FGF2, INF-γ, TNF-α), neurological function, body composition, depression and quality of life." (PMID 25563584, 2015). "A randomized controlled trial revealed that antidepressant treatment with the selective serotonin reuptake inhibitor (SSRI), sertraline, significantly decreased not only depression scores, but also baseline measurements of CRP and IL-6 in depressed subjects." (PMID 26550011, 2015). "Several studies have reported higher serum levels of the inflammatory cytokines IL-6, IL-1 and TNF- α in depression and AD." (PMID 25793613, 2015). "Peripheral/serum levels of IL-6 and TNF-α are increased in patients with depression, and these effects are normalized following antidepressant treatment." (PMID 25793613, 2015). "In a recent meta-analysis of allergy related cytokines in depression, IL1, IL4, IL6, and TNF-α, were found increased in depression compared to nondepressive study subjects and were considered to be a possible inflammatory link between the two disorders." (PMID 26783384, 2015). "Determine the serum levels of inflammatory markers (CRP, IL-6 and TNF-α) in elderly diabetic patients with depressive syndrome alone or with coexisting MCI." (PMID 25793613, 2015). "The aim of the study was to determine the serum levels of CRP, IL-6 and TNF-α in elderly diabetic patients with depressive syndrome alone or with coexisting mild cognitive impairment (MCI)." (PMID 25793613, 2015). "The investigated pro- and anti-inflammatory cytokines TNF, IL-6, IL-8, and IL-10 as well as DOR were expressed in skin from the upper and lower leg of patients with FMS, depression, and healthy controls." (PMID 25240423, 2014). "A meta-analysis performed on patients meeting the DSM criteria for major depression has shown higher concentrations of the proinflammatory cytokines TNF-α and IL-6 in depressed subjects compared to control subjects." (PMID 24723864, 2014). "Chronic inflammation has been suggested as an important mechanism related to depression, such as: C-reactive protein (CRP), interleukin-6 (IL-6), IL-1, IL-18." (PMID 25061971, 2014). "Our results indicated that 6 weeks of CUMS exposure induced significant depression-like behavior, with low 5-HT and NE levels, high TNF-α and IL-6 in brain and high hippocampal TNF-α, IL-6, P-NF-κBP65, and 5-HT2AR levels, and low BDNF expression levels." (PMID 25587342, 2014). "Moreover, some studies indicated that depression and psychological stress may induce an immune function imbalance and stimulate the production of proinflammatory cytokines, such as interleukin (IL)-1, IL-6 and tumor necrosis factor (TNF)." (PMID 25551389, 2014). "Our findings supported the association between elevations of proinflammatory cytokines such as IL-6 and TNF-α and major depression." (PMID 25237578, 2014). "Depression and psychological stress are characterised by elevated levels of IL-6 and TNF-α, and IL-6 stimulates cortisol secretion by adrenocortical cells." (PMID 24731917, 2014). "Depression and anxiety were analyzed using the Hospital Anxiety and Depression Scale (HADS), and serum levels of IL-1β, IL-6, IL-8, IL-10, IL-12, TNF-α, and TGF-β were measured by Cytometric Bead Array." (PMID 25309921, 2014). "Proinflammatory cytokines, such as IL-1β, IL-6, and TNF-α, also elicit adverse behavioral effects (fatigue, soporific effects) and symptoms of anxiety and depression." (PMID 24348675, 2013).
depression (continued). "Lastly, in subjects with a lifetime history of depression, IL-6 and CRP serum levels were found to be elevated, where IL-6 methylation in WBC DNA showed an inverse correlation with circulating IL-6 and CRP." (PMID 23977113, 2013). "For example, a recent meta-analysis found a significant correlation between tumor necrosis factor (TNF-α), IL-6, and CRP with depression in humans." (PMID 23382717, 2013). "Levels of IL-6 and CRP have been shown to be elevated in individuals with depression and decreased after antidepressant treatment." (PMID 23676005, 2013). "Elevated levels of proinflammatory cytokines, specifically IL-6, TNF-α, as well as C-reactive protein, seem to have a broad role in HF, depression, and CogI." (PMID 22919538, 2012). "Prior evidence supports that the development of depression is related to the levels of proinflammatory cytokines TNF-α and to interleukin-6 (IL6, the 33rd) in the brain." (PMID 21494644, 2011). "Meta-analyses and systematic reviews corroborate these findings, showing increased levels of interleukin-6 (IL-6), interleukin-8 (IL-8), tumor necrosis factor-alpha (TNF-α), and C-reactive protein (CRP) across major psychiatric disorders, including depression, anxiety, schizophrenia, and BD." (PMID 41598300, 2026). "At baseline, depression was significantly correlated with TNF-α, IL-6, and IL-1β." (PMID 41600880, 2026). "Moreover, MGO administration increased the levels of cytokines (IL-1β, IL-6, and TNF-α) in the serum, which led to neuropsychiatric disorders and depression as shown in behavior tests (i.e., OFT, TST, and FST)." (PMID 41355970, 2026). "Lep exhibited the ability to reduce serum LPS, IL-6, and TNF-α levels in stressed mice and repair the colonic mucosal injury, confirming that Lep can modulate systemic and neuro-inflammation, thereby alleviating the depression-like behavior." (PMID 39856996, 2025). "Similarly, increased concentrations of IL-1β, IL-6, and TNF-α have been reported in older adults with depression and across different depressive subtypes." (PMID 41333345, 2025). "A meta-analysis of 107 studies in the general adult population found that individuals with depression had elevated C-reactive protein (CRP), interleukin (IL)-3, IL-6, IL-12, IL-18, soluble interleukin 2 receptor (sIL-2R), and tumor necrosis factor alpha (TNF-α) levels with medium-effect sizes." (PMID 39902492, 2025). "Overall, the findings of these studies suggest that a range of cytokines, including IL-6, IL-10, TNF-α, and IL-8, may be involved in the pathophysiology of depression and that further research is needed to understand their roles fully." (PMID 40821647, 2025). "In the present study however, we did not observe significant relationships between symptoms of depression and IL-6 concentration." (PMID 41050477, 2025). "For example, in women who had just given birth, those with a lifetime history of MDD had greater increases in serum levels of IL-6 and soluble IL-6 receptors than those without a history of depression." (PMID 40336842, 2025). "Depression, IPF, frailty and peripheral inflammation at baseline and after follow-up were evaluated by indicators and scales such as BDI-II, FVC %pred, 6MWT, mMRC, CFS, TFI, SGRQ, K-BILD, IL-6, and TNF-α." (PMID 40120048, 2025). "On the other hand, inflammatory mechanisms might have a role in the etiology of depression, with plasma levels of pro-inflammatory cytokines such as TNF, IL-1, and IL-6 predicting its onset." (PMID 39941688, 2025). "It has been mentioned in many studies related to the pathogenesis of depression that the activation of microglial in the prefrontal cortex or hippocampus and the release of pro-inflammatory factors such as IL-1β, TNF-α and IL-6 in depressed animals with stress models." (PMID 40336842, 2025).